CXCL13 (C-X-C motif chemokine ligand 13)
Diseases named in the same sentence as CXCL13 in open-access papers (continued):
Sharing a sentence is not in itself a finding about the gene and the disease.
salpingitis (1 paper, 2020). Acute or chronic inflammation of the fallopian tube. "Thus, increased CXCL13 levels may promote or sustain plasma cell aggregates previously observed in tissues from women with chlamydial endometritis and salpingitis." (PMID 32127796, 2020).
severe combined immunodeficiency (1 paper, 2015). Severe combined immunodeficiency (SCID) comprises a group of rare monogenic primary immunodeficiency disorders characterized by a lack of functional peripheral T lymphocytes resulting in early-onset severe respiratory infections and failure to thrive. "A549-Luc-CXCL13 cells were injected into the right lung of the non-obese diabetic/severe combined immunodeficiency (NOD/SCID) mice (whose macrophages were functionally immature), and bioluminescence was recorded 30 days later." (PMID 26565418, 2015).
sialadenitis (1 paper, 2021). Sialadenitis is an infection of the salivary glands. "Although further studies are needed to elucidate the mechanisms underlying the overexpression of CXCL13 and CXCL12 in epithelial cells, the present results indicate that the CD153 vaccine is also effective for preventing age- and SS-related sialadenitis." (PMID 33669065, 2021).
signet ring cell carcinoma (1 paper, 2025). A usually aggressive, poorly differentiated invasive adenocarcinoma characterized by the presence of malignant glandular cells in which the nucleus is pressed to one side by the presence of intracytoplasmic mucus. "CXCL13 has been identified as a critical regulator of immune cell recruitment and differentiation within the TME in GC patients with signet ring cell carcinoma." (PMID 40406143, 2025).
sleep disorder (1 paper, 2019). A change from the patient's baseline sleeping pattern, in the hours slept and/or an alteration/dysfunction in the stages of sleep. "ROC curves show that neurological signs and sleep disorders appeared when CSF neopterin concentrations were above 21.20 nmol/L (AUC = 0.79 and 0.81, respectively) and/or CXCL-13 concentrations were above 330.26 pg/mL (AUC = 0.78 and 0.80, respectively)." (PMID 31886231, 2019).
soft tissue tumors (1 paper, 2017). "In order to compared the performance of FDCSP and SRGN with known FDC-S markers in the differential with soft tissue tumors, we tested CD21, CD23, CD35, CXCL13, Clusterin, Claudin 4 and Podoplanin in our groups of tumors and controls." (PMID 28145886, 2017). "In our study the combination of CXCL13, CD21, CD35, FDCSP and SRGN reached a very good discriminatory power in distinguishing FDC-S from other soft tissue tumors." (PMID 28145886, 2017). "The highest specificity was observed for SRGN, CXCL13 and for complement and Fc receptors (CD21, CD35 and CD23): they were negative in all soft tissue tumors used as controls." (PMID 28145886, 2017).
status epilepticus (1 paper, 2023). Status epilepticus is defined as a continuous seizure lasting more than 30 min, or two or more seizures without full recovery of consciousness between any of them. "Recent studies have demonstrated an increase in CXCL13 in rodent models of status epilepticus and postulated that this may play a role in pathogenesis." (PMID 37936721, 2023).
temporal lobe epilepsy (1 paper, 2021). A localization-related (focal) form of epilepsy characterized by recurrent seizures that arise from foci within the temporal lobe, most commonly from its mesial aspect. "CXCR5, the only known receptor for the chemokine CXCL13, is known to mediate neuroinflammation and thereby contribute to impairment of learning and memory in intractable temporal lobe epilepsy patients and pilocarpine-induced epileptic rats." (PMID 34711216, 2021).
teratoma (1 paper, 2022). A non-seminomatous germ cell tumor characterized by the presence of various tissues which correspond to the different germinal layers (endoderm, mesoderm, and ectoderm). "Evidence has suggested that in the acute phase of anti-NMDAR encephalitis, the content of CXCL13 in CSF increased significantly, and was related to older age, presence of infection symptoms before onset, combined with teratoma, and poor immunotherapy effect." (PMID 36389787, 2022).
testicular cancer (1 paper, 2017). A primary or metastatic malignant neoplasm that affects the testis. "Most of the studies on testicular cancer have focussed on tumour immunity and have shown that B cells and B-cell-supporting cytokines, such as IL-6 and CXCL-13, are involved in the immunopathology of testicular germ cell neoplasia." (PMID 28900475, 2017).
thoracic tumors (1 paper, 2023). "The combination of CXCL13 and VTQ for diagnosing thoracic tumors had an AUC of 0.842 (0.74, 0.94), which was significantly higher than either factor alone." (PMID 37025603, 2023).
tick-borne encephalitis (1 paper, 2019). Tick-borne encephalitis is caused by an arbovirus of the Flaviviridae family (tick-borne encephalitis virus, TBEV), transmitted principally by the bite of the Ixodes ricinus tick. "We investigated 26 patients with bacterial (n = 10) and viral (n = 16; tick-borne encephalitis, n = 6; varicella zoster infection, n = 10) neuroinfections of whom CSF CXCL13 levels were available twice, from lumbar punctures (LP) performed at admission and follow-up." (PMID 30660201, 2019).
tongue cancer (1 paper, 2020). A malignant neoplasm affecting the tongue. "The sequencing and PCR results in the present study confirmed that the expression levels of CXCL10, CXCL13 and other chemokines in tongue cancer tissues were significantly increased, suggesting their importance in tongue cancer." (PMID 32236620, 2020).
trigeminal neuralgia (1 paper, 2016). Trigeminal neuralgia is a nerve disorder that causes a stabbing or electric-shock-like pain in parts of the face. "Thus, targeting the CXCL13/CXCR5/ERK/TNF-α and IL-1β pathway in the TG may provide a novel therapeutic approach for the treatment of the trigeminal neuralgia." (PMID 27401148, 2016).
tuberculous meningitis (1 paper, 2021). "The patient with tuberculous meningitis had CSF CXCL13 concentrations of 361 pg/ml in the CXCL13 ELISA and 571 pg/ml in the recomBead CXCL13 assay." (PMID 34132584, 2021). "Two (8.0%) of them had elevated CSF CXCL13 levels; one was diagnosed with definite LNB, the other one was the one diagnosed with tuberculous meningitis." (PMID 34132584, 2021).
uterine tumors (1 paper, 2021). "In support of this, a study in ovarian and uterine tumors showed that increased TMB was associated with increased infiltration of CD8+ T cells expressing CXCL13 and TLS development." (PMID 35145509, 2021).
varicella (1 paper, 2017). "Two of these patients were diagnosed with varicella by PCR amplification in the CSF and their CXCL13 levels were 239.9 and 145.1 pg/ml." (PMID 28859668, 2017).
Wernicke encephalopathy (1 paper, 2020). An acute neurological disorder characterized by the triad of ophthalmoplegia, ataxia, and disturbances of mental activity or consciousness. "In sharp contrast, lack of CXCL13 in CSF despite severe BCSFB disruption in the spondylodiscitis and Wernicke encephalopathy patients indicated a sole peripheral focus of the CXCL13-associated inflammation." (PMID 32089130, 2020).
X-linked agammaglobulinemia (1 paper, 2025). X-linked agammaglobulinemia (XLA) is a clinically variable form of isolated agammaglobulinemia, an inherited immunodeficiency disorder (see this term), and is characterized in affected males by recurrent bacterial infections during infancy. "This explanation is unlikely because the levels of CXCL13 in X-linked agammaglobulinemia (XLA) patients, a condition characterised by antibody failure, are similar to those of healthy donors." (PMID 41288852, 2025).
tumor (635 papers, 2008 to 2026). "In high-risk PCa, the secretion of chemokine CXCL13 promoted increased B cell infiltration within the tumor, with B lymphocytes playing a role in the development of castration-resistant PCa by generating lymphotoxins." (PMID 40843359, 2025). "The involvement of LTβ and genes responding to LTβR signaling, such as CXCL13, suggest an active role of the LTβ–LTβR pathway in tumor-associated endothelium and lymphoid organogenesis as previously reported." (PMID 40897896, 2025). "Considering the association between CXCL13 and pathological response, we explored the role of CXCL13 in the anti-tumor effect of immunochemotherapy in vivo." (PMID 40295492, 2025). "A higher proportion of CXCL13 + T cells was associated with better outcomes and a stronger anti-tumor response." (PMID 41457151, 2025). "Genetic inhibition of ACLY increased tumour infiltration by B cells and upregulated the B cell chemoattractant CXCL13, promoting the formation of TLSs, immune niches associated with favourable prognosis in HCC and other solid tumours." (PMID 40739358, 2025). "In the TME, CXCL13 is a hallmark of tertiary lymphoid structures (TLSs), which facilitate antigen presentation and support effective anti-tumour T-cell responses." (PMID 40361472, 2025). "TPH cell cGEP usage was associated with CXCL13 expression and plasma cells abundance across tumors, indicating a role in tumor-associated lymphoid aggregates." (PMID 40903640, 2025). "Transcriptomic and spatial profiling in mice and humans linked reduced tumour ACLY with increases in the chemokine CXCL13, tumour-infiltrating B cells and tertiary lymphoid structures." (PMID 40739358, 2025). "In this study, we prioritized TCR candidates based on two key features associated with tumor reactivity: high clonal expansion and transcriptomic signatures such as CXCL13 expression and the NeoTCR8 signature score." (PMID 41294842, 2025). "In metastatic urothelial carcinoma, the status of ARID1A mutation and CXCL13 expression in tumour tissues predicted the clinical responses to immune checkpoint therapy." (PMID 40621620, 2025). "The coexistence of TLS and CXCL13+CD103+CD8+ TRM‐like cells in tumor tissues is associated with improved response to anti‐PD‐1 therapy." (PMID 41361844, 2025). "Pre-treatment CXCL13+ tumor-reactive T cells were associated with a favorable response to ICIs in TNBC, and were significantly expanded after treatment with chemotherapy combined with ICIs." (PMID 38533207, 2024). "For example, CXCL13+ tumor reactive T cells were the only subpopulation that associated with favorable response to ICIs." (PMID 38533207, 2024). "Elevated serum CXCL13 levels showed significant diagnostic potential, correlating with tumor characteristics." (PMID 39344390, 2024). "CXCL13, also known as B lymphocyte chemokine, is primarily derived from Tfh cells but can also be secreted by tumor-associated cells, such as macrophages, DCs, and specific CD8+ T cells." (PMID 39840050, 2024). "Immune Response and Prognosis: CXCL9, CXCL10, and CXCL13 are linked to favorable prognosis due to their role in enhancing the immune response at the tumor site, suggesting their potential as biomarkers for immune contexture in cancer." (PMID 39546375, 2024). "A study with multiple solid tumor types used single-cell meta-analysis to reveal a population of tumor-reactive CXCL13+ CD8+ T cells within tumors that was associated with improved response to immune checkpoint blockade." (PMID 38786066, 2024). "Elevated CXCL13 expression in human malignancies has been associated with various pathways and functions that contribute to tumor progression and immune responses." (PMID 39344390, 2024). "Accordingly, a rise in the CXCL13+ cell density within the mentioned compartments increases the risk of death and tumor progression." (PMID 38398098, 2024). "These two clusters, however, also displayed elevated CXCL13 expression, demonstrating that they were tumor-associated infiltrating CD8 T cells." (PMID 39256364, 2024).
tumor (continued). "uncovered key roles for TLS-associated B cells and CXCL13-expressing CD103+CD8+ tissue-resident memory T cells (Trm) in anti-tumor immunity." (PMID 39840050, 2024). "We also found that several of the downregulated genes including Ccl1, Ccl22, Cxcl13 or Ccr7 were associated with immunosuppression and decreased anti-tumour immunity." (PMID 37516803, 2023). "Turning to the RFS-related factors, the multivariate Cox regression analysis identified positive nodal status and large tumor diameter to be indicators of high risk of relapse, and the expression of CXCL13 mRNA as a factor protecting against relapse." (PMID 36765559, 2023). "Further incorporation of CXCL13 and CXCL10 tumor transcript levels in a 3-gene index revealed that high APRIL/CXCL10/CXCL13 expression was associated with improved OS in the TCGA SKCM cohort (HR = 0.42, 95% CI 0.19-0.94; p = 0.035)." (PMID 37435077, 2023). "CXCL13/CXCR5-associated immune processes are fundamentally involved in anti-tumor defense, and the effector cells of the axis are all but irrelevant side-targets of anti-PD-1 therapy." (PMID 36836910, 2023). "CCL19, CXCL10, and CXCL13 transcript expression levels were significantly associated with tumor stage (lowest levels in stage 2) in the TCGA-SKCM cohort." (PMID 37435077, 2023). "Despite such findings, the effects of CXCL13 expression on clinical outcomes remain controversial, particularly in terms of the association between high infiltration of CXCL13+ CD8+ T cells in tumor lesions and poor clinical outcomes." (PMID 38077321, 2023). "The expression of CXCL13 in tumor cells was also significantly associated with treatment response (p = 0.043)." (PMID 36650632, 2023). "This miRNA seem to inhibit CXCL13 (C-X-C motif chemokine ligand 13) and is associated with tumor staging and size." (PMID 37925534, 2023). "The expression levels of CXCL9 (P = 0.0201), CXCL11 (P = 0.0385), and CXCL13 (P = 0.0288) were significantly associated with tumor stage." (PMID 36798787, 2023). "High CXCL13 expression was associated with a larger tumor diameter and a shorter overall survival rate." (PMID 37240178, 2023). "CD4+ Th-CXCL13 recruits tumor-associated B cells and induces plasma cell differentiation and immunoglobulin production through interleukin-21 (IL-21) secretion and CD84 interactions in TLSs." (PMID 35663939, 2022). "Current evidence indicates that CXCL13 chemokine, originally discovered as a B-cell chemoattractant, is widely implicated in tumor development and progression." (PMID 36217194, 2022). "Although FDCs are the main source of CXCL13 in SLOs, the origin of CXCL13 in tumor associated TLS depends on the type of cancer." (PMID 35552285, 2022). "In particular, CXC ligand 1 (CXCL1), CXCL10 and CXCL13 have recently been associated with tumor survival, metastasis and angiogenesis." (PMID 36077611, 2022). "Tumor immune infiltration analysis showed that a high level of CXCL13 and corresponding high risk of LUAD were positively correlated with the activation of B cells, CD4+ T cells, CD8+ T cells, and dendritic cells." (PMID 35844446, 2022). "The 3 main model drivers were plasma G-CSF, CXCL13 and IL-6 levels, with higher plasma amounts of these factors generally associating with larger 4T1 tumours." (PMID 35226704, 2022). "CXCL13+CD103+CD8+ tumor-infiltrating T cells are associated with B cell recruitment, TLS formation, and neoantigen burden." (PMID 35053457, 2022). "Conversely, inhibition of TGFβ receptors abrogated CXCL13 signaling in the tumor-associated T cells." (PMID 36217194, 2022). "They showed that inhibition of CXCL13 (C-X-C motif chemokine ligand 13), produced by tumor-associated fibroblasts present in TME suppresses PC tumor growth." (PMID 36618354, 2022). "In the tumor, deficiency of Satb1 intensively enhanced CXCL13 expression by mouse Tfh cells within intratumor TLS." (PMID 35880181, 2022).
tumor (continued). "The anti-tumor CD103-positive CD8-positive T cell subset has furthermore been associated with chemokine CXCL13 expression, and is in line with the co-expression with TIM-3 in our analysis." (PMID 36341460, 2022). "CXCL13 secretion by macrophages is known to be associated with M2 phenotype and tumor-promoting properties." (PMID 36217194, 2022). "Transduction of tumor-associated FSCs by the viral vector precipitates profound activation and reprogramming of immunostimulatory Cxcl13-expressing FSCs." (PMID 34354077, 2021). "The production of CXCL13 by tumor-associated fibroblasts, Tfh cells, follicular dendritic cells (FDC) and HEV is positively-correlated with the formation of GC that contain CXCR5+ B cells." (PMID 34054879, 2021). "HER2 expression and amplification were positively associated with tumor‐infiltrating CXCL13‐positive ICs and CD20‐positive ICs as well as FOXP3‐positive ICs." (PMID 33506656, 2021). "The enrichment of CXCL13+ T cells in tumours with high mutational burden was supported by a second scRNAseq study and offers a possible explanation for why this patient cohort responds better to checkpoint blockade therapy." (PMID 34848830, 2021). "CXCL13 was upregulated in ccRCC tumor tissues and CXCL13 expression was associated with advanced stage and poor prognosis in ccRCC." (PMID 32986937, 2020). "In this study, we attempted to identify microenvironment-associated genes and explore the correlation between CXCL13 and tumor-infiltrating immune cells (TIICs)." (PMID 32669964, 2020). "Tumor-associated Tfh secrete CXCL13, attracting CXCR3+ CTLs and via IL-21 secretion promotes their effector functions." (PMID 33381121, 2020). "CXCL13 (C-X-C motif chemokine ligand 13) is related to cell proliferation and associated with poor prognosis in several neoplasms, including GC." (PMID 32117120, 2020). "These tumor-infiltrating CXCL13-producing TFH cells were linked with promoting local memory B cell differentiation, as well as with the expansion of a subpopulation of T regulatory cells." (PMID 31354634, 2019). "For instance, chromosomal instability in colorectal cancer can lead to deletion of the CXCL13 gene which is associated with greater risk of tumor relapse." (PMID 30873179, 2019). "The association between high median tumor CXCL13 content and favorable DDFS in TNBC was confirmed in the HE10/97 trial population (HR 0.30, 95% CI 0.09–0.93; P = 0.038)." (PMID 29482642, 2018). "We and others have reported significant association between high tumor CXCL13 content and favorable survival among patients with HER2-positive cancer not treated with trastuzumab." (PMID 29482642, 2018). "In univariable survival analyses, high tumor CXCL13 content was significantly associated with favorable DDFS in TNBC (HR 0.42, 95% CI 0.22–0.83, P = 0.012) unlike the other molecular subtypes." (PMID 29482642, 2018). "In TCGA cohort, CXCL13 expression was significantly associated with tumor size (P = 0.022), T stage (P < 0.001), N stage (P = 0.004), and M stage (P < 0.001)." (PMID 30723697, 2018). "Grouping by the GPS also showed a significant association with OS in patients with low tumor burden similar to serum CXCL13 level." (PMID 25966773, 2015). "BaP induced lung epithelial cells to secret CXCL13, which recruited tumor-associated macrophages (TAMs) and induced SPP1 production." (PMID 26565418, 2015). "As shown by immunohistochemistry, murine CXCL13 was associated with macrophage-like tumor-infiltrating cells that appeared to be histiocytes." (PMID 23936541, 2013). "Furthermore, CXCL13 expression is closely associated with the recruitment of CXCR5+ immune cells to tumor sites, directing and positioning them within lymphoid follicles, particularly CXCR5+ B cells." (PMID 41374956, 2025).